STEAP3 (STEAP3 metalloreductase)
Diseases named in the same sentence as STEAP3 in open-access papers (continued):
Sharing a sentence is not in itself a finding about the gene and the disease.
anemia (5 papers, 2019 to 2026). A reduction in the number of red blood cells, the amount of hemoglobin, and/or the volume of packed red blood cells. "Therefore, mutations in genes involved in endosomal iron uptake or export, such as DMT-1, the endosomal ferrireductase STEAP3, or Sec15L1 cause erythroblast iron deficiency and anemia." (PMID 34946818, 2021).
breast carcinoma (5 papers, 2020 to 2025). "While STEAP3 was unrelated to any improvement in overall breast cancer patient OS, other studies have found a relationship between downregulation of the related STEAP1, STEAP2, and STEAP4 proteins and improved outcomes." (PMID 37064114, 2023). "Subsequently, increased expression of STEAP3 was proved in a variety of tumor tissues, including breast cancer." (PMID 32802887, 2020). "Future efforts to more reliably and successfully treat this lethal breast cancer subtype will be built on the realization that the altered expression of STEAP3 in these individuals may have ramifications for overall survival and therapeutic strategies." (PMID 37064114, 2023). "However, no significant aberrant expression of STEAP3 was found in breast cancer tissues based on the analysis of ONCOMINE database." (PMID 32802887, 2020). "However, STEAP3 expression in non-TNBC cell lines, non-TNBC tissue and overall breast cancer patient cohorts indicated that this gene is not up-regulated or linked to the OS of these patients." (PMID 37064114, 2023).
cardiac hypertrophy (5 papers, 2021 to 2025). "Our study revealed a significant reduction of STEAP3 in both HF and AF, corroborating the results of earlier studies linking it to the negative regulation of pathological cardiac hypertrophy." (PMID 40672390, 2025). "A recent study revealed that STEAP3 ameliorates pathological cardiac hypertrophy by blocking the Rac1-MEK-ERK1/2 signaling cascade." (PMID 37524688, 2023). "Similarly, STEAP3 gene, essential in iron homeostasis, apoptosis, and inflammation, was reported as a key negative regulator of cardiac hypertrophy." (PMID 36769209, 2023).
colorectal cancer (5 papers, 2021 to 2024). A primary or metastatic malignant neoplasm that affects the colon or rectum. "A previous study showed that STEAP3 was overexpressed in colorectal cancer tissues and maintained the intracellular iron storage to promote proliferation." (PMID 37545464, 2024).
iron deficiency (5 papers, 2019 to 2025). "By facilitating the reduction of iron within the endosomes, STEAP3 helps regulate cellular iron levels, preventing both iron deficiency and toxicity." (PMID 40507980, 2025). "Steap3 is also thought to be important in immunity as iron deficiency confers resistance to the risk of infection." (PMID 35083470, 2021). "As Steap3 deletion abolished the ability of B cells to absorb and utilize extracellular Fe3+ (to Fe2+), we investigated whether iron deficiency was the cause for proliferation defects of Steap3-KO B cells." (PMID 31270335, 2019).
colon cancer (4 papers, 2021 to 2025). "We have developed a colon organoid-on-a-chip model using organoids derived from tissue specimens of patients with colon cancer to investigate the role of STEAP3 in viral infection within intestinal tissue." (PMID 40836050, 2025). "To accurately investigate the role of STEAP3 in viral infection within human intestinal tissues, we generated colon organoids derived from specimens of colon cancer patients." (PMID 40836050, 2025).
lung carcinoma (4 papers, 2016 to 2024).
microcytic anemia (4 papers, 2021 to 2025). Anemia in which the red blood cell volume is decreased. "Dysregulation of STEAP3 can disrupt iron homeostasis, as seen in patients with hypochromic microcytic anemia and iron overload, who harbor a nonsense mutation in their STEAP3 genes." (PMID 40507980, 2025). "COX15 is involved in the synthesis of heme a from heme b, while STEAP3 is iron transporter and its deficiency is associated with hypochromic microcytic anemia." (PMID 36836934, 2023). "Steap3 deficiency leads to impaired iron homeostasis and presents clinically as microcytic anemia with iron overload." (PMID 35083470, 2021). "Mice with a spontaneous STEAP3 deletion exhibit severe microcytic anemia, highlighting its essential role in iron homeostasis." (PMID 40836050, 2025).
clear cell renal cell carcinoma (3 papers, 2022 to 2023). "The expression of STEAP3 was substantially elevated and was shown to be linked to prognosis in the majority of malignancies, notably in clear cell renal cell carcinoma (ccRCC)." (PMID 37344930, 2023). "Subsequently, we constructed the competitive endogenous RNA (ceRNA) network that regulates STEAP3 expression in clear cell renal cell carcinoma (ccRCC) and validated the bioinformatic results through in vitro experiments." (PMID 37344930, 2023).
liver cancer (3 papers, 2023 to 2025). An epithelial or non-epithelial malignant neoplasm that arises from the liver. "In another study of liver cancer, researchers found that STEAP3 promotes cancer cell proliferation by facilitating nuclear transport of EGFR." (PMID 38440354, 2024). "Data indicated that STEAP3 is relatively highly expressed in lung, renal, urothelial, prostate, breast, and liver cancers based on the HPA database." (PMID 37344930, 2023). "IHC data of 190 samples revealed that STEAP3 is highly expressed in lung, renal, urothelial, prostate, breast, and liver cancers." (PMID 37344930, 2023). "Additionally, targeting the iron metabolism pathway, through iron chelators, has shown promise in cancer therapies, especially in prostate and liver cancers, as STEAP3 is crucial for iron homeostasis in tumour cells." (PMID 39853609, 2025).
Cirrhosis (2 papers, 2017 to 2022). A chronic disorder of the liver in which liver tissue becomes scarred and is partially replaced by regenerative nodules and fibrotic tissue resulting in loss of liver function. "The mRNA expression of STEAP3 was significantly downregulated in HCV-infected cirrhotic HCC compared with the cirrhosis tissues, and SLC7A11 was no significant in HCV-infected cirrhotic HCC." (PMID 36229881, 2022). "To further investigate whether matrix stiffness involves in the regulation of STEAP3, we firstly observed its expression in a DEN + NMOR-induced rat model of cirrhosis and HCC." (PMID 36229881, 2022).
liver cirrhosis (2 papers, 2022 to 2023). "A study proposed that increasing the presence of six-transmembrane prostate epithelial antigen 3 (STEAP3) can cause ferroptosis and mitigate HCV-infection-induced liver cirrhosis." (PMID 38131014, 2023). "Compared with the liver cirrhosis tissues, SLC7A11 was also significantly upregulated and STEAP3 was downregulated in HCC (GSE45050)." (PMID 36229881, 2022).
neuroblastoma (2 papers, 2017 to 2023). Neuroblastoma (NB) is the most common solid, extracranial childhood tumor. "In a study on ferroptosis-related gene signatures associated with prognosis in neuroblastoma, STEAP3 was found to be highly expressed, and increased STEAP3 activity undoubtedly increased the amount of labile iron." (PMID 37736551, 2023). "In the present study the ferrireductase enzyme Steap3, and putative ferrireductase α-synuclein, were both associated with high APP amyloidogenic processing and β-amyloid production in neuroblastoma cells." (PMID 28187176, 2017).
non-alcoholic fatty liver disease (2 papers, 2023 to 2025). "The absence of STEAP3 has been shown to impede the progression of non-alcoholic fatty liver disease (NAFLD), whereas its overexpression can lead to lipid accumulation within hepatic cells." (PMID 40005907, 2025).
renal carcinoma (2 papers, 2021 to 2024). A carcinoma arising from the epithelium of the renal parenchyma or the renal pelvis. "In addition, STEAP3 is involved in the remodeling of the extracellular matrix and the formation of tumor immune microenvironment in renal cancer to promote tumor metastasis and immune evasion." (PMID 38440354, 2024).
renal cell carcinoma (2 papers, 2023 to 2024). "It has also been found that STEAP3 is significantly upregulated in renal cell carcinoma and is associated with poor prognosis." (PMID 38440354, 2024). "It has been also shown that STEAP3 expression is upregulated in renal cells and that it can affect the progression of renal cell carcinoma by regulating ferroptosis." (PMID 38440354, 2024). "Previous studies have shown that the knockdown of STEAP3 affects ferroptosis and renal cell carcinoma progression by regulating the Xc− system." (PMID 38440354, 2024).
uveal melanoma (2 papers, 2022). A melanoma derived from melanocytes of the uveal tract. "In uveal melanoma (UM), the expression of STEAP3 is significantly increased, and elevated STEAP3 was identified as a prognostic risk factor for UM." (PMID 36424540, 2022).
viral infection (2 papers, 2024 to 2025). "Collectively, these findings suggests that STEAP3 knockdown increases the susceptibility of both tissues and their surrounding microenvironment to viral infection." (PMID 40836050, 2025). "Our results suggest that STEAP3 deficiency increases the susceptibility of both intestinal tissues and their surrounding microenvironment to viral infection." (PMID 40836050, 2025). "Using this system, we observed that STEAP3 deficiency markedly enhanced viral infection in intestinal epithelium, especially enterocytes and enteroendocrine cells." (PMID 40836050, 2025). "Applying siSTEAP3 siRNA to organoids significantly reduced STEAP3 protein levels and enhanced the luciferase signal from SARS-CoV-2 S entry viruses, indicating that STEAP3 deficiency promotes viral infection." (PMID 40836050, 2025). "Building upon this approach, we applied this vascular system to colon organoids to construct a vascularized organoid model, enabling the investigation of the effects of STEAP3 deficiency on viral infection within the vasculature." (PMID 40836050, 2025). "In this vascularized colon organoids-on-chip model, STEAP3 knockdown led to increased viral infection within vascular lumens, suggesting that loss of STEAP3 may facilitate viral dissemination through the circulatory system." (PMID 40836050, 2025). "Virus-infected colon organoids underwent immunofluorescence staining with specific intestinal epithelial cell markers to identify cell types and were visualized under confocal microscopy with z-stacks to determine their susceptibility to STEAP3 knockdown in enhancing viral infection." (PMID 40836050, 2025). "Human intestinal tissues consist of multiple cell types, each of which may exhibit varying susceptibility to STEAP3 knockdown in promoting viral infection." (PMID 40836050, 2025). "Additionally, 3D reconstructed images showed that enterocytes and enteroendocrine cells of the intestinal epithelium exhibited increased susceptibility to viral infection following STEAP3 knockdown, as determined by the ratio of viral quantity to the positively stained area of intestinal markers." (PMID 40836050, 2025). "STEAP3 downregulation led to an increase in viral infection within the vascular network, as evidenced by the enhanced GFP signal within vascular lumens." (PMID 40836050, 2025). "Collectively, our biomimetic model of vascularized colon organoids provides a precise platform for studying the role of STEAP3 in viral infection within the intestinal epithelium and its surrounding microenvironment." (PMID 40836050, 2025). "To comprehensively investigate the role of STEAP3 in viral infection, we employed both 3D organoid systems and 2D cell cultures, and established a biomimetic 27-well colon organoid-on-chip platform as an efficient experimental model." (PMID 40836050, 2025). "Nevertheless, the downregulation of STEAP3 attenuated the antiviral effect of FAC on viral infection, suggesting that STEAP3 plays a role in FAC-mediated antiviral activity." (PMID 40836050, 2025). "Therefore, we examined whether STEAP3 also modulates the viral infection of SARS-CoV-2 variants." (PMID 40836050, 2025). "Taken together, these findings indicate that STEAP3 suppresses viral infection, potentially by impeding viral entry." (PMID 40836050, 2025). "Our findings demonstrate that STEAP3 exerts an inhibitory effect on viral infection, particularly during the viral entry phase, possibly through interactions with viral receptors." (PMID 40836050, 2025). "Given that FAC suppresses viral infection, these findings indicate that STEAP3 plays a key role in modulating FAC-induced antiviral activity." (PMID 40836050, 2025). "To further confirm the influence of STEAP3 at the early stage of viral infection, we utilized the SARS-CoV-2 S entry virus to investigate its effects on SARS-CoV-2 entry." (PMID 40836050, 2025).
viral infection (continued). "In this study, we leveraged both 3D and 2D model systems to comprehensively investigate the role of STEAP3 in regulating viral infection in intestinal tissues." (PMID 40836050, 2025). "Notably, STEAP3 knockdown significantly enhanced viral infection, as evidenced by an increased GFP signal in STEAP3-deficient vascularized organoids, particularly in regions adjacent to the organoids." (PMID 40836050, 2025). "Previously, we demonstrated that STEAP3 modulated viral infection at the entry stage." (PMID 40836050, 2025). "As STEAP3 possesses a six-transmembrane domain at its C-terminus and is predominantly localized to the plasma membrane, it may play a role in regulating viral infection at an early stage-viral entry." (PMID 40836050, 2025). "Therefore, it is reasonable to suggest that STEAP3 inhibits viral infection by modulating its interaction with viral receptors." (PMID 40836050, 2025). "Furthermore, this interaction gradually decreased over time, suggesting that STEAP3 binds to viral receptors during the early stage of viral infection." (PMID 40836050, 2025). "However, in the virus-infected mock cells, the mRNA levels of NCOA4, ACSL4, and STEAP3 considerably increased while being down-regulated in the DDX3X-silenced cells with virus infection." (PMID 39155369, 2024). "The expression of intestinal epithelial cell markers differs between colon epithelial cell lines and colon epithelial organoids, with notable variations in the expression levels of STEAP3 and the viral receptor ACE2, which may result different underlying mechanisms in response to viral infection." (PMID 40836050, 2025). "Since STEAP3 regulates iron homeostasis under physiological conditions and FAC induces iron overload, leading to reactive oxygen species-mediated apoptosis, we sought to investigate the role of STEAP3 in viral infection in the absence of FAC supplementation." (PMID 40836050, 2025).
adenomyosis (1 paper, 2025). The growth of endometrial tissue inside the muscular wall of the uterine corpus. "Genes that promote ferroptosis, such as ACSL1, ALOX15, STEAP3, and SLC11A2, were upregulated in adenomyosis." (PMID 40911580, 2025).
aneurysm (1 paper, 2021). Bulging or ballooning in an area of an artery secondary to arterial wall weakening. "Specifically, in a study of 6 participants with unruptured intracranial aneurysms, the authors observed a fold change > 2.5 with higher STEAP3 expression observed in aneurysm tissue." (PMID 35083470, 2021).
Arthritis (1 paper, 2025). Inflammation of a joint. "Immunofluorescence results demonstrated that STEAP3 expression was markedly elevated in OA cartilage, and that STEAP3 expression was also augmented in mouse models of DMM-induced arthritis." (PMID 41258082, 2025).
Burkitt lymphoma (1 paper, 2016). A rare form of malignant mature B-cell non-Hodgkin lymphoma. "In mouse models, STEAP3 overexpression in Raji cells, a line derived from Burkitt lymphoma, allowed the tumor growth to persist when low iron levels would normally encourage apoptosis." (PMID 27898674, 2016).
HCMV infection (1 paper, 2020). "During the late phase of HCMV infection, STEAP3, BORCS7, FAM172A, RELL1 and WDR48 were differentially expressed between Han- and HanUL138del-infected cells, and further functional studies indicated that all of these proteins could affect HCMV infection." (PMID 32481657, 2020). "Among these proteins, STEAP3, BORCS7, FAM172A, RELL1, and WDR48 were further demonstrated to affect HCMV infection." (PMID 32481657, 2020).
intracranial aneurysm (1 paper, 2021). "Interestingly, however, STEAP3 has been identified as a differentially expressed gene in the intracranial aneurysm wall compared with a control tissue of the superficial temporal artery." (PMID 35083470, 2021).
lymph node metastasis (1 paper, 2023). "STEAP3 was significantly associated with age, stage, grade, lymphovascular space invasion (LVSI), and lymph node metastasis (LNM) in patients with OC." (PMID 37386521, 2023).
muscle disorders (1 paper, 2025). "However, there is no direct evidence linking STEAP3 dysfunction to specific muscle disorders." (PMID 40507980, 2025).
nephrotoxicity (1 paper, 2025). Toxicity that causes injury to the kidney or damages its function. "The expression of TFRC, ACSL4, and STEAP3, all of which promote ferroptosis, was significantly upregulated in the APAP-induced nephrotoxicity group." (PMID 41249093, 2025).
Obesity (1 paper, 2021). Accumulation of substantial excess body fat. "In humans, the gene has been linked to obesity, while in sheep, STEAP4 and other members of the same gene family (STEAP3) have been associated with excess fat accretion in tails." (PMID 34529728, 2021).
ovarian tumor (1 paper, 2024).